MYSM1 (Myb like, SWIRM and MPN domains 1)
Diseases named in the same sentence as MYSM1 in open-access papers (continued):
Sharing a sentence is not in itself a finding about the gene and the disease.
osteoporosis (4 papers, 2016 to 2024). A condition of reduced bone mass, with decreased cortical thickness and a decrease in the number and size of the trabeculae of cancellous bone (but normal chemical composition), resulting in increased fracture incidence. "While Mysm1-deficient mice exhibit bone deformities and osteoporosis, their MSCs maintain normal osteogenic differentiation capacities in vitro." (PMID 39684760, 2024). "The altered balance between normal osteogenesis and adipogenesis by MSCs may also contribute to osteoporosis in Mysm1 deficient mice." (PMID 26915790, 2016). "The genetic silencing of astrocytic Mysm1 induced an antidepressant‐like effect and alleviated the osteoporosis of depressive mice." (PMID 36414403, 2022). "The knockdown of astrocytic Mysm1 relieved murine depressive‐like behaviors and alleviated the osteoporosis of depressive mice." (PMID 36414403, 2022). "Astrocytic but not neural knockdown of Mysm1 relieves murine depressive‐like behaviors and surprisingly alleviates osteoporosis." (PMID 36414403, 2022). "Mysm1−/− mice exhibit significant skeletal deformation and osteoporosis; however, osteogenic differentiation capacity was not significantly affected in MSCs lacking Mysm1." (PMID 36093077, 2022). "Mysm1 may represent a potential therapeutic target for controlling MSC lineage differentiation, and possibly for the treatment of metabolic bone diseases such as osteoporosis." (PMID 26915790, 2016).
B cell lymphoma (3 papers, 2021 to 2024). "We recently established that the loss of MYSM1 in mouse models of cMYC-driven B cell lymphoma can protect against disease onset and progression." (PMID 36611064, 2023). "We demonstrate that in cMYC‐driven B cell lymphoma in mouse models, MYSM1‐loss represses ribosomal protein gene expression and protein synthesis." (PMID 34114734, 2021). "This firmly establishes that loss of MYSM1 inhibits the oncogenic activity of cMYC, and protects against B cell lymphoma onset and progression in mouse models." (PMID 34114734, 2021). "Overall, we establish that the loss of MYSM1 protects against B cell lymphoma onset and progression in the EuMyc mouse model via a reduction in the expression of genes encoding the ribosomal and translational machinery." (PMID 34114734, 2021). "Importantly, the loss of MYSM1 also strongly inhibits cMYC oncogenic activity and protects against B cell lymphoma onset and progression in the mouse models." (PMID 34114734, 2021). "The binding of MYSM1 and cMYC at the shared sites was also confirmed in cells derived from EuMyc mouse B cell lymphoma, specifically for the Rpl7 and Eef1g gene promoters (data not shown)." (PMID 34114734, 2021). "This suggests MYSM1 as a potential drug target for B cell lymphoma and possibly other haematologic malignancies with cMYC‐locus rearrangements and amplifications." (PMID 34114734, 2021). "Taken together, our work demonstrates that MYSM1 is required to sustain the oncogenic activity of cMYC in B cell lymphoma, by promoting the cMYC‐dependent induction of the genes encoding ribosomal proteins and translation factors." (PMID 34114734, 2021).
Immunodeficiency (3 papers, 2018 to 2025). Failure of the immune system to protect the body adequately from infection, due to the absence or insufficiency of some component process or substance. "Moreover, humans with deficiency in HELLS display life-threatening immunodeficiency, centromeric instability, and facial anomalies (ICF) syndrome reminiscent of the phenotype of Lsh-deficient mice that share certain traits with Mysm1-deficient mice." (PMID 32466590, 2020). "HSCT is still the conventional treatment for MYSM1 related BMF and immunodeficiency; it holds the promise for lifesaving HSCT but with many challenges including graft versus host disease (GVHD) and complications from conditioning regimens." (PMID 40535318, 2025).
lymphopenia (3 papers, 2015 to 2020). Reduction in the number of lymphocytes. "The studies also found that Mysm1-knockout mouse lines mimic the symptoms of human aplastic anemia, lymphopenia, and thrombocytosis." (PMID 32354135, 2020). "Myb Like, SWIRM And MPN Domains 1 (Mysm1) knockout mice exhibit a phenotype with a severe bone marrow (BM) hematopoietic defect, which leads to the development of lymphopenia, anemia, and thrombocytosis." (PMID 33327527, 2020).
autoimmune disease (2 papers, 2021 to 2024). A disorder resulting from loss of function or tissue destruction of an organ or multiple organs, arising from humoral or cellular immune responses of the individual to their own tissue constituents. "Myb-like swi/snf complex member 1 (MYSM1) is a key suppressor of innate immunity and autoimmunity and represents a potential therapeutic agent for infectious, inflammatory, and autoimmune diseases." (PMID 39517176, 2024). "In addition, targeted approaches are being developed based on the modulators of the cGAS-STING pathway such as the immunosuppressor MYSM1, which may be considered as a therapeutic target for inflammatory and autoimmune diseases." (PMID 33708225, 2021).
cataract (2 papers, 2020 to 2022). Partial or complete opacity of the crystalline lens of one or both eyes that decreases visual acuity and eventually results in blindness. "MYSM1 knock‐out mice showed aging‐like phenotypes manifested as shorter body lengths, lower body weights, cataracts and eye diseases, smaller spleen, and abnormal livers." (PMID 33240758, 2020). "Mysm1−/− mice developed dull and partially white eyes, with cataracts and eye diseases developing within 1 to 6 months that rapidly progressing from 6 to 11 months." (PMID 33240758, 2020).
colon adenocarcinoma (2 papers, 2019 to 2021). "Notably, MYSM1 expression in adjacent normal tissues derived from 349 colon adenocarcinoma (COAD) and 318 rectal adenocarcinoma (READ) patients was significantly higher than that in 275 COAD and 92 READ specimens." (PMID 34706761, 2021).
leukemia (2 papers, 2015 to 2020). A malignant (clonal) hematologic disorder, involving hematopoietic stem cells and characterized by the presence of primitive or atypical myeloid or lymphoid cells in the bone marrow and the blood. "Similarly, increased numbers of γH2AX foci, the redistribution of MYSM1, and the colocalization of MYSM1 with γH2AX foci occurred in KG-1a leukemia cells treated with 10 μM etoposide for 2 h." (PMID 32466590, 2020).
Osteopenia (2 papers, 2016 to 2020). Osteopenia is a term to define bone density that is not normal but also not as low as osteoporosis. "Abnormalities in the in vitro differentiation of Mysm1-/- mesenchymal stem cells (MSCs), such as enhanced adipogenesis, were also reported, and could be functionally linked to osteopenia and skeletal abnormalities in Mysm1-deficiency." (PMID 32344625, 2020). "The decreased amount of trabecular bone and thinner cortices confirmed the existence of osteopenia in the Mysm1−/− mice." (PMID 26915790, 2016). "Mysm1−/− mice show characteristic osteopenia, a condition that became more severe with age." (PMID 26915790, 2016).
prostate tumors (2 papers, 2017 to 2019). "We observed that MYSM1 were downregulated in CRPC compared to localized prostate tumors." (PMID 31761786, 2019).
Sepsis (2 papers, 2016 to 2026). Sepsis is defined as life-threatening organ dysfunction caused by a dysregulated host response to infection. "Overall, our study elucidates the role of MYSM1-mediated dysregulation of epigenetic modifications in the immune response during the late phase of sepsis, providing a novel therapeutic approach for addressing sepsis-related immune dysfunction." (PMID 41678561, 2026).
skin atrophy (2 papers, 2015 to 2018). The degeneration and thinning of the epidermis and dermis. "Skin atrophy correlated with reduced proliferation rates in Mysm1−/− epidermis and hair follicles, and increased apoptosis compared with wild-type controls, along with increases in DNA-damage marker γH2AX." (PMID 29495602, 2018).
acute myeloid leukemia (1 paper, 2023). Acute myeloid leukemia (AML) is a group of neoplasms arising from precursor cells committed to the myeloid cell-line differentiation. "In acute myeloid leukemia (AML) relapse, circRNF220 acts as a pathogenic factor by sponging miR-30a and upregulating MYSM1." (PMID 37838643, 2023).
Alzheimer disease (1 paper, 2024). A progressive, neurodegenerative disease characterized by loss of function and death of nerve cells in several areas of the brain leading to loss of cognitive function such as memory and language. "Additionally, increased MYSM1 expression has been observed in mouse models of chronic restraint stress (CRS), Alzheimer’s disease (AD), and Parkinson’s disease (PD) (unpublished data)." (PMID 39684760, 2024).
blood disease (1 paper, 2023). A disease that occurs in the blood. "However, a recent study demonstrated that human HSC is sensitive to ferroptosis under blood disease conditions, due to the absence of the histone deubiquitinase MYSM1." (PMID 37227070, 2023).
brain tumors (1 paper, 2021). "In addition, MYSM1 downregulation was observed in kidney and brain tumors." (PMID 34706761, 2021).
colitis (1 paper, 2020). Inflammation of the colon. "Of note, Mysm1-/- adipose-derived stem cells were also recently shown to produce higher levels of inflammatory cytokines and to exacerbate the pathology of colitis in mouse models, although MYSM1 regulation of miR150-expression was proposed as the underlying mechanism." (PMID 32344625, 2020).
diffuse large B-cell lymphoma (1 paper, 2019). "In addition, MYSM1 expression was higher only in DLBC (lymphoid neoplasm diffuse large B-cell lymphoma) and THYM (thymoma) than that in normal tissues." (PMID 31761786, 2019).
Griscelli syndrome (1 paper, 2014). Griscelli syndrome (GS) is characterized by silvery gray sheen of the hair and hypopigmentation of the skin which can be associated to neurological impairment (type 1), immunodeficiency (type 2) or be isolated (type 3). "In-depth analysis of three mutants, Krt76, Myo5a (a model of human Griscelli syndrome) and Mysm1, provides validation of the screen." (PMID 24721909, 2014).
heart failure (1 paper, 2025). Inability of the heart to pump blood at an adequate rate to meet tissue metabolic requirements. "Within this dataset, the mRNA expression of MYSM1 was elevated in heart failure (HF) group compared to the control normal heart (NHF) group." (PMID 39897566, 2025).
infarct (1 paper, 2025). "Mysm1-/+ mice also resulted in a reduction of myocardial infarct area and serum cardiac injury markers compared to WT mice following chronic I/R injury." (PMID 39897566, 2025).
inflammatory bowel disease (1 paper, 2019). A spectrum of small and large bowel inflammatory diseases of unknown etiology. "In the present study, we demonstrate that Mysm1‐deficient ASCs showed attenuated inhibition of T cell proliferation in vitro, while exacerbating inflammatory bowel diseases and inhibiting tumour growth in vivo." (PMID 30895711, 2019). "Mysm1‐deficient ASCs exacerbated inflammatory bowel diseases but inhibited tumour growth in vivo." (PMID 30895711, 2019).
metastatic melanoma (1 paper, 2017). A melanoma that has spread from its primary site to another anatomic site. "According to the data analyses, nuclear MYSM1 was detectable in the majority of malignant primary and metastatic melanoma cases." (PMID 28978033, 2017).
microcephaly (1 paper, 2024). A congenital or acquired developmental disorder in which the circumference of the head is smaller than normal for the person's age and sex. "Mice with Mysm1 knockdown by crossing Mysm1 floxed mice with Nestin-Cre mice exhibited abnormal brain development with microcephaly." (PMID 38342917, 2024).
mucinous adenocarcinoma (1 paper, 2021). An invasive adenocarcinoma composed of malignant glandular cells which contain intracytoplasmic mucin. "Moreover, upon analyzing the different histological subtypes, we found that compared with tubular adenocarcinoma (TA) or adenocarcinoma (A), mucinous adenocarcinoma (MA), which is among the worst pathological subtypes in terms of the clinical prognosis of CRC, barely expressed MYSM1." (PMID 34706761, 2021).
myocardial infarct (1 paper, 2025). "Cardiomyocyte-specific knockdown of MYSM1 also resulted in a reduction of myocardial infarct area and serum cardiac injury markers following chronic I/R injury." (PMID 39897566, 2025). "Mysm1-/+ mice had reduced myocardial infarct area compared to WT mice following I/R injury." (PMID 39897566, 2025).
Pancytopenia (1 paper, 2021). An abnormal reduction in numbers of all blood cell types (red blood cells, white blood cells, and platelets). "The patient with a novel MYSM1 variant (P1) suffered worsening pancytopenia and unfortunately died from post-transplant complications." (PMID 34539671, 2021).
prostate adenocarcinoma (1 paper, 2019). "The expression of MYSM1 was decreased in PRAD (prostate adenocarcinoma) compared with that in normal prostate glands, but the change was not statistically significant." (PMID 31761786, 2019).
scoliosis (1 paper, 2021). A congenital or acquired spinal deformity characterized by lateral curvature of the spine. "Some candidates, such as DHX40, NBPF20, RASA2, and MYSM1, have been found to be associated with syndromes with scoliosis or implicated in bone/spine development." (PMID 34440387, 2021).
systemic lupus erythematosus (1 paper, 2024). An autoimmune multi-organ disease typically associated with vasculopathy and autoantibody production. "The higher proportion of Flt3+ B1 cells in systemic lupus erythematosus (SLE) patients suggests a potential role of the MYSM1/miR-150/Flt3 pathway in the pathogenesis of SLE." (PMID 39684760, 2024).
tumor (15 papers, 2016 to 2025). "Studies indicate that a deficiency or reduced expression of MYSM1 in several cancers suggest its tumor-suppressive function." (PMID 39684760, 2024). "In mouse models, Mysm1-deficient AD-MSCs exacerbated inflammatory bowel disease but suppressed tumor growth." (PMID 39684760, 2024). "Conversely, several studies have demonstrated that elevated MYSM1 expression is associated with cancer progression, enhancing tumor growth." (PMID 39684760, 2024). "Li Y and his colleagues reported that MYSM1 expression is significantly elevated in carcinoma tissues and is associated with tumor progression in CRC." (PMID 34706761, 2021). "Consistently, xenograft study that investigated the effect of MYSM1 deficiency in 22Rv1 cells revealed a significant increase of tumor volume, suggesting an antitumorigenic role for MYSM1 in CRPC." (PMID 31761786, 2019). "To follow up on our observations of increased spontaneous and induced DNA damage in various cell types of Mysm1-deficient mice, and of altered MYSM1 expression in tumor cells, we used a mass spectrometry-based proteomics approach to explore MYSM1 functions in DNA damage responses." (PMID 32466590, 2020). "In addition, the tumor marker CA199 was also shown to be positively associated with MYSM1 positive expression (P = 0.007), suggesting that MYSM1 expression in tumor cells is a potential predictive factor for CRC." (PMID 28498834, 2017). "MYSM1 staining in tumor cells and associations with clinicopathologic characteristics." (PMID 28498834, 2017). "In brief, MYSM1 is positively associated with tumorigenesis and liver metastasis of tumor cells." (PMID 28498834, 2017). "In in vivo tumor models, Mysm1-deficient macrophages display characteristics of M1 macrophages and suppress tumor growth, indicating MYSM1’s crucial role in macrophage survival and polarization and meaning it could potentially serve as a target for cell therapy." (PMID 39684760, 2024). "Secondly, given MYSM1’s involvement in hematopoiesis, immune regulation, neural development, and tumor development, further investigation is needed to elucidate the specific tissues and organs directly influenced by MYSM1 in terms of development and function." (PMID 39684760, 2024). "Previous studies have explored the role of MYSM1 in various cancer models, revealing its potential oncogenic and tumor-suppressive properties." (PMID 39684760, 2024). "To better investigate the potential correlation between MYSM1 and tumors, we first performed IHC on a series of tumor and normal tissue microarrays to identify variations in the expression level of MYSM1." (PMID 34706761, 2021). "Collectively, these data indicate that MYSM1 inhibits tumor progression in CRC cells by activating miR-200 family members." (PMID 34706761, 2021). "MYSM1 expression levels in CRC cell lines and tumor tissues were detected, and their associations with patient survival rate and clinical stage were analyzed using databases and tissue microarrays." (PMID 34706761, 2021). "The results showed that neoplasm growth was greatly enhanced by Mysm1 knockout but markedly suppressed by MYSM1 overexpression in vivo." (PMID 34706761, 2021). "To further confirm the functional impact of MYSM1 on tumor growth, we performed IHC staining to analyze tumor tissues from nude mice." (PMID 31761786, 2019). "The observation that the MYSM1 expression decreases as the tumor develops castration resistance led us to evaluate the role of MYSM1 in CRPC." (PMID 31761786, 2019). "Taken together, these findings suggest a potential role of MYSM1 in the biological interaction network correlated with tumor progression." (PMID 31761786, 2019). "We found that MYSM1 levels are downregulated in CRPC tissues compared to localized primary tumor tissues, indicating a potential role for MYSM1 in the switch to castration resistance." (PMID 31761786, 2019).